NSD2 (nuclear receptor binding SET domain protein 2)
Diseases named in the same sentence as NSD2 in open-access papers (continued):
Sharing a sentence is not in itself a finding about the gene and the disease.
colorectal cancer (10 papers, 2021 to 2025). A primary or metastatic malignant neoplasm that affects the colon or rectum. "In microsatellite instability-high (MSI-H) colorectal cancers, NSD2 undergo frameshift mutations, resulting in the loss of protein expression." (PMID 41301842, 2025). "We found that conditional knockout of NSD2 in intestinal epithelial cells inhibited the progression of colorectal cancer in mice." (PMID 38400589, 2025). "In colorectal cancer, NSD2 overexpression accelerates cell proliferation and migration by increasing global H3K36me2 levels and several cancer-promoting genes, such as ADAM9, EGFR, and MET." (PMID 41301842, 2025). "Originated from exons 1 and 2 of the NSD2 gene, circ‐NSD2 is overexpressed in colorectal cancer tissues, particularly in advanced stages or metastatic tumors." (PMID 40761890, 2025). "The inhibition of NSD2-mediated PTEN methylation sensitizes tumor cells to DNA-damaging agents in combination with a PI3K inhibitor in colorectal cancer." (PMID 41301842, 2025). "We transfected the pll3.7‐shNSD2 vector into the mouse colorectal cancer cell line MC38 to induce NSD2 knockdown." (PMID 38400589, 2025). "Our results showed that conditional knockout of NSD2 in intestinal epithelial cells inhibited the progression of colorectal cancer in mice." (PMID 38400589, 2025). "Circ‐NSD2 upregulates JAG1 in colorectal cancer, while circ_0006476 modulates DLL4 in atherosclerosis, illustrating how circRNAs regulate Notch ligands to amplify pathway activity across diseases." (PMID 40761890, 2025). "In colorectal cancer, NSD2 silencing downregulates MHC-1 levels and inactivates IFN-γ/STAT1 signaling, thereby impairing antitumor immunity." (PMID 41301842, 2025). "Conditional knockout of NSD2 in intestinal epithelial cells significantly inhibits colorectal cancer progression." (PMID 38400589, 2025). "In conclusion, we established a model of colorectal cancer in which intestinal epithelial cells were subjected to conditional NSD2 knockout." (PMID 38400589, 2025). "Because H3K36me2 controls gene expression and affects DNA repair, NSD2‐mediated H3K36me2 is essential for the transcriptional activation and expression of multiple oncogenes to support the development of colorectal cancer." (PMID 38400589, 2025). "The nuclear receptor binding domain protein 2 (NSD2) is a key histone methyltransferase, and its expression in colorectal cancer is related to the proliferation and migration of colorectal cancer." (PMID 37020597, 2023). "NSD2 circular RNA aggravates liver metastasis of colorectal cancer by regulating miR-199b-5p/DDR1/JAG1 axis." (PMID 37709489, 2023). "In colorectal cancer, NSD2 (Nuclear Receptor Binding SET Domain Protein 2) circular RNA inhibits miR-199b-5p expression, which leads to an upregulation of DDR1 expression and promotes migration and invasion in vitro and in vivo." (PMID 33917302, 2021). "Not only is this model a powerful tool to study the pathogenesis of colorectal cancer, but also our findings indicate that NSD2 may serve as a target for new therapeutic strategies for colorectal cancer." (PMID 38400589, 2025). "Therefore, knockout of NSD2 can inhibit the progression of colorectal cancer by reducing the levels of inflammatory cytokines." (PMID 38400589, 2025). "This shows that NSD2 plays a critical role in the process of colorectal cancer progression and could be a potential therapeutic target for colorectal cancer." (PMID 38400589, 2025). "Therefore, NSD2 regulates the AKT signaling pathway by mediating the H3K36me2 modification of gene loci in colorectal cancer." (PMID 38400589, 2025). "After the CRISPR/Cas9 knockout of NSD2, the proliferation and development of colorectal cancer were inhibited, suggesting that NSD2 could be a potential target for the treatment of colon cancer." (PMID 37020597, 2023).
colorectal cancer (continued). "In fact, another circRNA (circ-NSD2), also derived from WHSC1, was reported to promote migration, invasion and metastasis of colorectal cancer (CRC) cells in a mouse model of CRC liver metastasis, highlighting that this family of circRNAs derived from WHSC1 may be worth further investigation." (PMID 34199580, 2021). "We found that knockout of NSD2 significantly reduced the concentrations of IL‐6, TNF‐α, and TGF‐β1 in the serum of mice with colorectal cancer." (PMID 38400589, 2025). "Additionally, NSD2 can also directly methylate PTEN and enhance the DNA damage repair ability in colorectal cancer, and enhance the resistance of cancer cells to chemotherapy." (PMID 37024523, 2023). "Moreover, NSD2 directly methylates active regulator of SIRT1 (AROS) at K27 to facilitate its interaction with SIRT1, resulting in SIRT1 activation and enhanced fatty acid oxidation in colorectal cancer." (PMID 41301842, 2025).
lung cancer (10 papers, 2016 to 2025). A malignant neoplasm involving the lung. "To verify whether the knock down of NSD2 in the lung cancer cell line H1299 causes similar changes in histone methylation we conducted mass spectrometry analysis to monitor the status of histone H3 K36 methylation in combination with K27 methylation that can be readily detected on the same peptide." (PMID 27604143, 2016). "In KRAS-driven lung cancer, inactivation of NSD2 by the oncohistone H3K36M leads to activation of an antiviral-like immune response through SETD2-mediated H3K36me3 deposition." (PMID 41301842, 2025). "In lung cancer cells, inhibition of NSD2-mediated H3K36me2 results in growth retardation by suppressing KRAS-driven transcriptional program." (PMID 41301842, 2025). "We show that NSD2 is involved in the proliferation of several lung cancer RAS-mutant cell lines, whereas it seems of lesser importance in cells that do not have RAS mutations." (PMID 27604143, 2016). "Here, we describe that NSD2 contributes to the proliferation of a subset of lung cancer cell lines by supporting oncogenic RAS transcriptional responses." (PMID 27604143, 2016). "Here, we describe that NSD2 contributes to the proliferation of a subset of lung cancer cell lines by altering oncogenic RAS transcriptional responses." (PMID 27604143, 2016). "We next evaluated potential consequences of NSD2 knock down in the lung cancer cell line H1299 that expresses high levels of NSD2." (PMID 27604143, 2016). "Despite the fact that NSD2 has been reported to be frequently overexpressed in lung cancer, the contribution of NSD2 to the malignancy of this disease is poorly understood." (PMID 27604143, 2016). "To understand how PD0325901, JQ1 and NSD2 depletion cooperate to prevent the growth of lung cancer cells we analyzed by RNA-seq the changes in gene expression caused by the individual treatments and in combination." (PMID 27604143, 2016). "In lung cancer patients, NSD2 overexpression and uncontrolled H3K36me2 enrichment lead to rapid tumor progression and also to a poorer outcome, and NSD2 inhibition disrupts the activation of RAS-target genes, contributing to the inhibition of the RAS-mediated oncogenic transcriptional programs." (PMID 36232375, 2022). "To verify whether lung cancer cell lines could recapitulate the same phenomena as lung tumors we screened the expression of NSD2 by western blot in a panel of cell lines that were available in our laboratory." (PMID 27604143, 2016). "This makes NSD2 an attractive candidate for lung cancer therapy." (PMID 27604143, 2016). "Moreover, depletion of NSD2 in other lung cancer cell lines with RAS activating mutations and high levels of NSD2 had antiproliferative effects, further confirming the impact of NSD2 on the transcriptional responses of oncogenic RAS in lung cancer cell lines." (PMID 27604143, 2016). "Thus, combinatorial therapies using MEK or BRD4 inhibitors together with NSD2 inhibition are likely to be needed to ensure a more comprehensive inhibition of oncogenic RAS-driven transcription programs in lung cancers with NSD2 overexpression." (PMID 27604143, 2016).
colon cancer (9 papers, 2021 to 2025). "For example, NSD2, a known oncogenic gene in colon cancer, has been identified as a colon-specific E3 ligase (P-value of Mann–Whitney U-test = 8.96E-80)." (PMID 39395186, 2024). "qRT-PCR assay results demonstrated that NSD2 mRNA levels in colon cancer tissues were significantly higher than those in normal tissues." (PMID 34671018, 2021). "As shown, NSD2 mRNA levels in colon cancer tissues (n = 275) were significantly higher than those in normal colon tissues (n = 349)." (PMID 34671018, 2021). "Results showed that NSD2 protein upregulation in colon cancer tissues was significant (P < 0.05 vs. normal tissues)." (PMID 34671018, 2021). "A catalytic inactive NSD2 (Y1179A) also inhibited H3K36me2, multiple oncogenes expression, and Akt activation, as well as cell proliferation and migration in primary colon cancer cells." (PMID 34671018, 2021). "Contrarily, ectopic NSD2 overexpression in primary colon cancer cells further enhanced cell proliferation, migration, and invasion." (PMID 34671018, 2021). "NSD2 mRNA and protein expression is significantly elevated in human colon cancer tissues, whereas relatively low NSD2 expression is detected in match surrounding normal tissues." (PMID 34671018, 2021). "Gene Expression Profiling Interactive Analysis (GEPIA) bioinformatics results showed that the NSD2 mRNA expression is elevated in both colon cancers and rectal cancers." (PMID 34671018, 2021). "H3K36me2, expressions of multiple oncogenes (ADAM9, EGFR, Sox2, Bcl-2, SYK, and MET) and Akt activation were significantly decreased after NSD2 silencing or knockout in primary colon cancer cells." (PMID 34671018, 2021). "Conversely, ectopic overexpression of NSD2 expedited proliferation and migration of colon cancer cells." (PMID 34671018, 2021). "Furthermore, NSD2 mRNA and protein expression levels in local colon cancer tissues are significantly higher than those in matched surrounding normal tissues." (PMID 34671018, 2021). "For example, NSD2 promotes tumor angiogenesis through methylating and activating STAT3 protein in colon cancer." (PMID 40097917, 2025). "In primary human colon cancer cells and established CRC cell lines, shRNA-induced silencing or CRISPR/Cas9-induced knockout of NSD2 inhibited cell viability, proliferation, cell cycle progression, migration, and invasion." (PMID 34671018, 2021).
developmental delay (9 papers, 2019 to 2025). "The core NSD2-associated phenotype includes mostly mild developmental delay, prenatal-onset growth retardation, low body mass index, and characteristic facial features distinct from WHS." (PMID 33941880, 2021). "NSD2 is associated with developmental delay/intellectual disability; however, its role in brain development and function remains unclear." (PMID 38419783, 2024). "Future studies may integrate GFAP scoring with detailed gene-level analyses to better understand how specific genes within the 4p16.3 region—such as NSD2 (associated with developmental delay), LETM1 (epilepsy), or CPLX1 (synaptic function)—modulate individual trajectories." (PMID 40725476, 2025). "In humans, NSD2 is located in a critical region of microdeletion 4p16.3 which is associated with Wolf-Hirschhorn syndrome, which presents with microcephaly at birth, global developmental delay, postnatal growth deficiency, ID, distinct craniofacial features, and seizures." (PMID 36845425, 2023). "Without the methylation signature, the variant may have taken far longer to identify; however, we appreciate that if the exome sequencing was performed today the likelihood of missing the frameshift variant in NSD2, in a child with mild delays and global developmental delays, would be low." (PMID 36589751, 2022). "De novo variation in NSD2 (also known as WHSC1) is thought to be related to diseases since identified in patients with a wide range of phenotypic features including developmental delay, autism, and congenital cardiac disorders." (PMID 31382906, 2019). "Loss of function mutations in NSD2 have been associated with ASD across multiple genetics studies, and replicate several of the clinical presentations of Wolf–Hirschhorn syndrome including microcephaly, global developmental delay, and ID, but do not present seizures." (PMID 36845425, 2023).
lung adenocarcinoma (7 papers, 2016 to 2024). A carcinoma that arises from the lung and is characterized by the presence of malignant glandular epithelial cells. "At the same time, we analyzed the mutation rates of H3K36 enzymes (including NSD1, NSD2, NSD3, ASH1L, SMYD2, SETDB2, SETD3, and SETMAR) in lung adenocarcinoma, which showed that the amplification mutation frequency of H3K36 enzymes was at a low level." (PMID 39119928, 2024). "The experimental results showed that the NSD2 depletion combined with the MEK1/2 inhibition treatment regimen can significantly inhibit KRAS-mutant lung adenocarcinoma tumors." (PMID 38275900, 2024). "Analysis of mRNA levels showed that NSD2 is significantly overexpressed in lung adenocarcinoma (AD) and squamous cell carcinoma (SCC) when compared with normal lung tissue obtained from the same patients." (PMID 27604143, 2016). "In lung adenocarcinoma, for example, there are activating mutations in the H3K36me2 KMT NSD2/MMSET." (PMID 38914477, 2024). "NSD2 knockdown could also inhibit the tumor growth in xenografts derived from patients with primary lung adenocarcinoma." (PMID 38275900, 2024).
microcephaly (7 papers, 2015 to 2023). A congenital or acquired developmental disorder in which the circumference of the head is smaller than normal for the person's age and sex. "Therefore, it is possible that during brain development, NSD2 could control the proliferation and cell fate decisions of NPCs which if impaired could be a mechanism contributing to the congenital microcephaly associated with deficits in NSD2." (PMID 36845425, 2023). "Therefore, it is possible that the microcephaly phenotypes in humans with mutations in NSD2 could arise from defects in NPC proliferation." (PMID 36845425, 2023). "In addition to the potential role of ASH1L in the control of brain size postnatally, clinical studies suggest that mutations in either NSD1, NSD2, SETD2, or SETD5 have also been implicated in microcephaly." (PMID 36845425, 2023).
Intellectual disability (6 papers, 2016 to 2024). "A novel loss of function NSD2 variant, c.1577dupG (p.Asn527Lysfs*14), was identified in a Chinese family in the proband and her father both affected with intellectual disability." (PMID 33276791, 2020). "Our results suggested NSD2 mutation might cause a distinct intellectual disability and short stature syndrome." (PMID 33276791, 2020).
osteosarcoma (6 papers, 2012 to 2025). A usually aggressive malignant bone-forming mesenchymal neoplasm, predominantly affecting adolescents and young adults. "Likewise, in osteosarcoma, the gain-of-function NSD2 mutations within the SET domain, including E1099K and Y1179A, exhibit a catalytically hyperactive state and promote tumor growth both in vitro and in vivo." (PMID 41301842, 2025). "In ccRCC cells and osteosarcoma cells, NSD2 silencing also decreased Akt phosphorylation." (PMID 34671018, 2021). "As a control, we also overexpressed H3.3G34R, which is found in glioblastoma and osteosarcoma, and which inhibits both SETD2 and NSD2 only locally in cis." (PMID 36052643, 2022).
epilepsy (5 papers, 2012 to 2025). A brain disorder characterized by episodes of abnormally increased neuronal discharge resulting in transient episodes of sensory or motor neurological dysfunction, or psychic dysfunction. "Candidate genes for epilepsy phenotype were identified in these regions, such as Wolf-Hirschhorn Syndrome Candidate 1 gene (WHSC1, current name Nuclear Receptor Binding SET Domain Protein 2 - NDS2) and Leucine Zipper And EF-Hand Containing Transmembrane Protein 1 gene (LETM1), respectively." (PMID 33987468, 2020). "In certain patients with the smallest micro-deletions in 4p16.3, a cluster of four genes including NSD2 and CTBP1 is deleted, implicating CTBP1 in neurodevelopmental disorders including epilepsy in some WHS patients." (PMID 33192249, 2020).
endometrial cancer (4 papers, 2018 to 2020). Primary or metastatic malignant neoplasm involving the endometrium (mucous membrane that lines the endometrial cavity). "Studies have shown that NSD2 is overexpressed in endometrial cancer compared to normal endometrium and is associated with adverse prognostic features." (PMID 33050946, 2020). "Although the oncogene MMSET (also known as NSD2 or WHSC1) has an essential role in malignancies, its impact on human endometrial cancer (EC) metastasis and the molecular mechanism of MMSET regulation are largely unknown." (PMID 29796186, 2018).
hepatocellular carcinoma (4 papers, 2018 to 2023). A malignant tumor that arises from hepatocytes. "WHSC1, which is a synonym for NSD2, is involved in morphogenesis of anatomic structure and associated with hematologic malignancies and hepatocellular carcinoma." (PMID 30620740, 2019).
lymphoma (4 papers, 2016 to 2025). A malignant (clonal) proliferation of B- lymphocytes or T- lymphocytes which involves the lymph nodes, bone marrow and/or extranodal sites. "Additional eight mutations that were significantly enriched in rHL/prHL affect genes that were previously associated with the progression of other lymphoma subtypes (e.g., PDGFRB, KAT6A, HGF, EPHB1, NSD2, PMS2)." (PMID 39992429, 2025). "Human protein atlas database suggested the overexpression of NSD2 in bone marrow cancer and lymphoma." (PMID 32826945, 2020). "Surprisingly, among BRCA1 mutation(s) discovered in lymphoma patients, BRCA1 K1183R prevented its translocation into the nucleus, failed to reduce NSD2 protein levels in hemin-treated K562 cells and eventually disrupted cell differentiation." (PMID 32826945, 2020).
mantle cell lymphoma (4 papers, 2015 to 2022). Mantle cell lymphoma is a rare form of malignant non-Hodgkin lymphoma affecting B lymphocytes in the lymph nodes in a region called the ``mantle zone''. "NSD2 is one of the most commonly mutated genes in mantle cell lymphoma, and it is associated with poor prognosis." (PMID 36232375, 2022). "Like NSD2, mutations in the SET domain of NSD3 (E1181K and T1232A), which counteract the auto-inhibition mechanism of H3K36 methylation, are associated with mantle cell lymphoma and chronic lymphocytic leukemia." (PMID 35581654, 2022).
metastatic disease (4 papers, 2014 to 2025). "In the mouse prostate, we found that Nsd2 protein is expressed at low levels in non-metastatic tumors from the NP mice, while it is highly expressed in metastatic tumors from the NPK mice, as well as corresponding metastases from these mice (n = 4/group)." (PMID 30518758, 2018).
prostate tumors (4 papers, 2019 to 2024). "AR and NSD2 transcriptional activities were also positively correlated in primary prostate tumors from the TCGA cohort (R = 0.68, P = 2.2 × 10−16)." (PMID 39251788, 2024). "Here, we present an epigenetic tumor-driven mechanism by which prostate tumors remain relatively cold due to increased levels of the epigenetic enzyme NSD2." (PMID 38062230, 2023).
Rauch-Steindl syndrome (4 papers, 2021 to 2026). "Rauch-Steindl syndrome (RAUST) is a very rare genetic syndrome caused by pathogenic variants in the NSD2 gene on chromosome 4p16.3." (PMID 42221011, 2026). "Larger structural variants (SVs) involving NSD2 are associated with Wolf–Hirschhorn 4p16.3 deletion syndrome, and loss-of-function (LoF) and missense variants in NSD2 were recently associated with the developmental disorder Rauch–Steindl syndrome." (PMID 38318288, 2023). "The WHS candidate 1 (WHSC1) gene, also known as NSD2, is located in the WHSC and has been reported to associate with Rauch-Steindl syndrome (RSS,OMIM 619695)." (PMID 37351323, 2023).